KDM8 (lysine demethylase 8)
Diseases named in the same sentence as KDM8 in open-access papers (continued):
Sharing a sentence is not in itself a finding about the gene and the disease.
tumor (24 papers, 2012 to 2026). "Additionally, loss of KDM8 expression is correlated with increased expression of cell cycle genes that may contribute to deranged cell cycle regulation and tumor progression." (PMID 31036064, 2019). "Rigorous transplanted tumor studies employing multiple in vivo models demonstrated that Kdm8 and KDM8 knockdown in both murine and human PDA cell lines, respectively, increased PDA metastasis." (PMID 40909661, 2025). "Third, stochastic depletion of Kdm8 in the malignant cells within a tumor enabled major transcriptomic and histological changes that are associated with Kdm8 loss." (PMID 40909661, 2025). "Consistent with the subcutaneous tumor experiments, KDM8 knockdown promoted liver metastasis in these orthotopic PDA tumor models." (PMID 40909661, 2025). "KDM8 expression decreased as tumor malignant grade increased in that stage 1 tumors had the highest median KDM8 values." (PMID 31036064, 2019). "To further validate KDM8 as a critical coactivator of AR in prostate carcinogenesis, we wish to identify the recruitment of KDM8 to the promoters of AR target genes involved in tumor progression." (PMID 30072740, 2019). "KDM8 overexpressing and vector control LNCaP cells were injected into athymic nu/nu mice and the tumor growth was monitored." (PMID 30072740, 2019). "To see whether the hypermorphic Kdm8 variants have an even stronger anti-metastatic effect, we performed orthotopic tumor studies using Kdm8 knockout 688M and 606T PDA cells." (PMID 40909661, 2025). "For each PTCKdm8KO tumor (total n=7), we detected a minimum of 80% indel (insertion and deletion) formation at the Kdm8 targeted site estimated by the Surveyor nuclease assay, thus validating the effectiveness of the current method in deleting Kdm8." (PMID 40909661, 2025). "In addition, Lysine Demethylase 8(KDM8) is a potential tumor suppressor downregulated in HCC and is a downstream target of HNF4α signaling." (PMID 36249028, 2022). "KDM8 exerts tumor suppressive functions in hematopoietic cancer by mediating DNA repair." (PMID 31036064, 2019). "We therefore asked whether KDM8 is able to modulate the tumor metabolism in PCa cells." (PMID 30072740, 2019). "Together, these observations suggest that KDM8 may function as a tumor suppressor." (PMID 31036064, 2019). "In sum, we demonstrate that tumor-related exon-10 mutations in PKM2 conferred altered conformation near the C–C interface region, a substantial decrease of allosteric regulation, and increased interaction with KDM8, facilitating nuclear translocation and transactivation." (PMID 30911680, 2019). "The mean methylation of CpGs in two genes is hypomethylated in normal and hypermethylated at the terminal tumor regions (USP44 and SATB2); the opposite is true for three other genes (KRBA1, ANKS4B, and KDM8)." (PMID 37120552, 2023). "Compared to the other Kdm family members, Kdm8 knockdown with two independent short hairpin RNAs (shRNAs) reproducibly promoted lung metastasis without affecting subcutaneous primary tumor growth." (PMID 40909661, 2025). "In this investigation, three tumor-related mutants, H391Y, R399E, and G415R18,33–35, were chosen to characterize the allostery and nuclear translocation activity and its relationship with KDM8." (PMID 30911680, 2019). "These TFs play central roles in cell polarity maintenance and epithelial differentiation, hence down-regulation of KDM8 may drive epithelial–mesenchymal transition (EMT) and tumor progression." (PMID 31036064, 2019). "Interestingly, we reported that KDM8 facilitates the nuclear translocation of PKM2 (pyruvate kinase M2 isoform), a critical enzyme involved in tumor metabolism." (PMID 30072740, 2019). "Prognostic significance of KDM8 was also independent of tumor stage." (PMID 31036064, 2019). "At the beginning, we used immunohistochemical stain analysis to determine the expression status of the KDM8 and CCNA1 protein in 27 OSCC samples TMA and 5 normal oral mucosa samples adjacent to the tumor." (PMID 37893043, 2023).
KDM8 also shares sentences with these, for which no sentence is quoted: hepatocellular carcinoma (5 papers); Intellectual disability (3); colon cancer (2); leukaemia (2); pancreatic ductal adenocarcinoma (2); anemia (1); asthma (1); Bloom syndrome (1); brain arteriovenous malformations (1); chronic kidney disease (1); colon (1); Failure to thrive (1); glioma (1); hematopoietic cancer (1); lung adenocarcinoma (1); neurodevelopmental disorder (1); prostate tumors (1); stomach adenocarcinoma (1).